PRDM1 (PR/SET domain 1)
Diseases named in the same sentence as PRDM1 in open-access papers (continued):
Sharing a sentence is not in itself a finding about the gene and the disease.
gastric cancer (3 papers, 2015 to 2024). A primary or metastatic malignant neoplasm involving the stomach. "Applying databases of cBioPortal and CCLE for proper in vitro validation, we found human stomach cancer cell lines tended to have greater BRD4 expressions once their PRDM1 expressions were higher, with this association also being observed in the TCGA STAD dataset." (PMID 38540967, 2024). "Whether BRD4 loss resulted from PRDM1 knockdown rendering stomach cancer insensitive toward IBET151 was of concern, so further testing found shPRDM1-SNU-1 displayed decreased sensitivity toward IBET151 while this inhibitor showed an obvious suppression on shLuc-SNU-1 in terms of proliferation." (PMID 38540967, 2024). "On the contrary, the role of PRDM1 in GI cancers has been less reported and our systematic bioinformatic analysis showed that its high expression in stomach cancer further predicted poor prognosis." (PMID 38540967, 2024). "While a few inhibitors possibly counteracting PRDM1-high stomach cancer were discovered, the most frequent ones were those for epigenetics, with the targets of these epigenetic inhibitors all pointing to BET protein." (PMID 38540967, 2024). "PRDM1 expression thus indicated the potential effectiveness of BET inhibitors in stomach cancer treatment, as similar therapeutics have entered clinical trials." (PMID 38540967, 2024). "Cell-line experimentation indeed validated that PRDM1 knockdown in human stomach cancer cell line SNU-1 decreased BRD4 expression, proliferation, and sensitivity to BET inhibitor." (PMID 38540967, 2024). "Further therapeutic and pathway analyses revealed that PRDM1-high stomach cancer might be targeted by BET inhibitor and was enriched for chromatin remodeling-related features." (PMID 38540967, 2024). "Summarizing the present study from systematic bioinformatic analysis for chromatin remodeling-related factors in GI cancers, we found PRDM1 in stomach cancer was the only pair showing expression alteration and prognosis prediction out of 31 candidate genes and six GI cancer types." (PMID 38540967, 2024). "Our focus on PRDM1 in stomach cancer via systematic bioinformatic analysis and in vitro validation could add additional clues to chromatin remodeling factor-regulated stomach cancer appraisal." (PMID 38540967, 2024). "In the present study, we identified chromatin remodeling-related PRDM1 as a contributor to stomach cancer formation via modulations on cell proliferation and BRD4 expression; specifically, via systematic bioinformatic analysis on the chromatin remodeling-related gene list suggested by our team." (PMID 38540967, 2024). "This demonstrates that PRDM1 is detectable in stomach cancer in another independent cohort, and with up-to-date RNA sequencing on biopsy or even liquid biopsy, the expression of PRDM1 could serve as a factor in the prediction of stomach cancer development and BET inhibitor treatment." (PMID 38540967, 2024). "We additionally validated the positive correlation between PRDM1 and CD274 (programmed death ligand 1) in stomach cancer in the TCGA dataset (Figure A15)." (PMID 38540967, 2024). "Following bioinformatic analysis, we performed cell-line experiments to confirm the effects of PRDM1 on proliferation, BRD4 expression, and response to IBET151 in stomach cancer." (PMID 38540967, 2024).
Hodgkins lymphoma (3 papers, 2020 to 2023). A heterogeneous group of malignant lymphoid neoplasms of B-cell origin characterized histologically by the presence of Hodgkin and Reed-Sternberg (HRS) cells in the vast majority of cases. "In classical Hodgkin lymphoma, PRDM1 is induced directly by FOXOs, so it seemed plausible that the overlapping patterns of gene and pathway dysregulation were in part caused by a similar relationship in pre-B cells." (PMID 36670235, 2023).
liver cancer (3 papers, 2022 to 2024). An epithelial or non-epithelial malignant neoplasm that arises from the liver. "(B) Heatmap of the ordered, z-score normalized expression values for PRDM1 and NK cell-associated genes in liver cancer patients." (PMID 39133873, 2024). "The present study unveiled a novel regulatory mechanism of Prdm1 in cNK cells and liver ILC1s, showing promising potential for developing innovative immune therapy strategies against liver cancer." (PMID 39133873, 2024). "Ultimately, they applied single-cell RNA sequencing on liver cancer specimens and validated the relationship between PRDM1 expression and liver cancer immunity as well as treatment response." (PMID 38540967, 2024). "To examine other molecular mechanisms, we inoculated murine liver cancer cells (Hepa1-6 and H22) into immunodeficient mice (BALB/c nude mice); tumor proliferation was distinctly slower in the Prdm1 group and was faster in the sgPrdm1 groups than in the corresponding controls." (PMID 36509766, 2022).
lymphoid tumours (3 papers, 2016 to 2023). "The transcription factor PRDM1 is a master regulator of plasma cell development and is considered to be an oncosuppressor in several lymphoid neoplasms." (PMID 32985591, 2020). "Therefore all were selected for further functional analysis together with BACH2 and PRDM1, which had been implicated as TSG in lymphoid tumours and are positioned within the 6q15-6q21 deletion hot-spot." (PMID 36670235, 2023).
ovarian carcinoma (3 papers, 2020 to 2024). A malignant neoplasm originating from the surface ovarian epithelium. "Beyond that, higher expression of PRDM1 predicted a worse prognosis in ovarian cancer." (PMID 35935940, 2022). "Through the gene regulatory networks analysis, we speculated that PRDM1 may be involved in CD8+ T cells exhaustion and predicted that its high expression in ovarian cancer was associated with poor prognosis." (PMID 35935940, 2022). "Indeed, verified by bulk RNA-seq from the TCGA dataset, it was a slightly significant Spearman correlation between PRDM1 expression and immune exhausted infiltrate in ovarian cancer (Cor:0.41, FDR: 2e−12)." (PMID 35935940, 2022). "However, little is known about the role of PRDM1 in ovarian cancer." (PMID 38607753, 2024). "PRDM1 regulators may be involved in T cell exhaustion in ovarian cancer." (PMID 35935940, 2022). "As evidenced by CHIP-PCR, we found that the TF binding site (TFBS) of five TFs had binding events to BRD4 after it was cultured with or without CM of ovarian cancer cells, among which PRDM1 and MAF had increasing binding events after CM treatment." (PMID 32184777, 2020).
T Cell Lymphoma (3 papers, 2014 to 2017). "Although research on PRDM1 in NK/T-cell lymphoma is rapidly increasing, few studies have examined PRDM1 in Asian EN-NK/T-NT patients, which constitute a large portion of the incidence of this disease in the world." (PMID 24438193, 2014). "The ectopic expression of miR-223 led to the downregulation of the PRDM1 protein in the NK/T-cell lymphoma cell line, whereas a decrease in miR-223 restored the level of PRDM1 protein." (PMID 24438193, 2014). "To further clarify the molecular mechanism of PRDM1 inactivation, we compared the PRDM1 protein expression with the PRDM1 transcript level in EN-NK/T-NT specimens and NK/T-cell lymphoma cell lines." (PMID 24438193, 2014). "Similarly, both qRT-PCR and western blot analysis revealed the discrepancy between PRDM1 transcript and its protein in some NK/T-cell lymphoma cell lines." (PMID 24438193, 2014). "The downregulation of PRDM1 protein in B and T cell lymphomas may be ascribed to different mechanisms." (PMID 24438193, 2014). "The mechanism for inactivation of positive regulatory domain containing I (PRDM1), a newly identified tumour suppressor gene in extranodal NK/T-cell lymphoma, nasal type (EN-NK/T-NT) has not been well defined." (PMID 24438193, 2014).
Achalasia (2 papers, 2016 to 2023). A disorder of esophageal motility characterized by the inability of the lower esophageal sphincter to relax during swallowing and by inadequate or lacking peristalsis in the lower half of the body of the esophagus. "Besides, many co-inhibitory molecules, including PDCD1, HAVCR2, LAG3, ICOS, PRDM1, and MAF, were markedly downregulated in TRM, supporting an activated cell state in achalasia." (PMID 37542039, 2023).
acute graft versus host disease (2 papers, 2022 to 2024). A syndrome of immunologically mediated tissue damage that may occur following an allogeneic transplant, usually affecting the skin, liver, and GI tract. "Here, we found low expression of PRDM1 in T cells from donor and recipients both related to the occurrence of acute graft-versus-host disease (aGVHD)." (PMID 35572579, 2022).
AIDS (2 papers, 2021 to 2025). A syndrome resulting from the acquired deficiency of cellular immunity caused by the human immunodeficiency virus (HIV). "Of note, PRDM1 has also been demonstrated to be induced in various cell types from AIDS patients during HIV infection (51, 67, –, 69)." (PMID 34488445, 2021). "Interestingly, PR/SET domain 1 (Prdm1, also known as Blimp1), a DNA-binding protein expressed in neonatal IECs or induced in AIDS patients, acts as a tether/sequestration factor by recruiting XR_001779380 to form the Prdm1/Stat1/Pias1 complex." (PMID 40497734, 2025).
Alzheimer disease (2 papers, 2025). A progressive, neurodegenerative disease characterized by loss of function and death of nerve cells in several areas of the brain leading to loss of cognitive function such as memory and language. "Previous studies have connected GATA2 to rheumatism, and PRDM1 may be associated with Alzheimer’s disease development." (PMID 41007174, 2025). "Together these observations show a strong overlap of PRDM1 DEGs with gene signatures relevant to Alzheimer’s disease progression and pathology." (PMID 41278975, 2025).
Azoospermia (2 papers, 2016 to 2020). Absence of any measurable level of sperm,whereby spermatozoa cannot be observed even after centrifugation of the semen pellet. "Examples are over-expression of deleted in azoospermia (DAZ), DAZL, BOULE, DDX4, PR/SET domain 1 (PRDM1), DPPA3, and nanos C2HC-type zinc finger 3 (NANOS3)." (PMID 32033159, 2020).
central nervous system lymphoma (2 papers, 2016 to 2024). "Deleterious mutation of one of the ZNF family members, PRDM1 has been associated with primary central nervous system lymphoma." (PMID 27829003, 2016).
chronic lymphocytic leukemia (2 papers, 2017 to 2019). "PRDM1 gene expression was consequently significantly upregulated in CD4+ and CD8+ T-cells in chronic lymphocytic leukemia patients but not in their leukemic B-cells." (PMID 30654767, 2019).
Cryptosporidium infection (2 papers, 2021 to 2025). "Given the limitation of the murine models of intestinal cryptosporidiosis, the immunological significance for Prdm1 in intestinal cryptosporidiosis warrants future investigations using enteroids derived from humans." (PMID 34488445, 2021). "Our findings support that antisense oligonucleotides targeting the Prdm1-XR_001779380 interaction promote IFN-γ-stimulated gene transcription and enhance cell-intrinsic defense against Cryptosporidium infection." (PMID 40497734, 2025). "Moreover, antisense oligonucleotides (ASOs) targeting the Prdm1-XR_001779380 interaction can promote IFN-γ-stimulated gene transcription and enhance cell-intrinsic defense against Cryptosporidium infection." (PMID 40497734, 2025).
encephalitis (2 papers, 2022 to 2024). An acute inflammatory process affecting the brain parenchyma. "Myositis and encephalitis, both, were associated with alterations of PRDM1 and CD274, which might explain their joined appearance in clinical practice." (PMID 35053465, 2022). "Finally, CNVs on PRDM1 and CD274 were significantly linked to encephalitis, and CNVs on PRDM1, CD274, TSHR and FAN1 were significantly linked to myositis." (PMID 35053465, 2022). "CNVs on PRDM1 and CD274 were significantly linked to encephalitis (p = 0.014 and p = 0.032) and myositis (p = 0.014 and p = 0.032)." (PMID 35053465, 2022). "The occurrence of myositis as well as encephalitis was associated with CNVs on CD274 and PRDM1 in our study, possibly explaining the combined occurrence of these IRAE in clinical practice." (PMID 35053465, 2022). "Of note, the association of CNVs on PRDM1 to encephalitis and myositis has not been reported in the literature yet." (PMID 35053465, 2022). "Regarding CNVs, significant markers included PRDM1 deletions and IL1RN (IRAE), CD274 duplications and SLCO1B1 (hepatitis), PRDM1 and CD274 (encephalitis), and PRDM1, CD274, TSHR, and FAN1 (myositis)." (PMID 35053465, 2022). "Furthermore, the following genetic alterations were identified being associated with IRAE: SMAD3 (pancreatitis); CD274, SLCO1B1 (hepatitis); PRDM1, CD274 (encephalitis); PRDM1, CD274, TSHR, FAN1 (myositis)." (PMID 35053465, 2022).
glomerulonephritis (2 papers, 2017 to 2025). A renal disorder characterized by damage in the glomeruli. "Importantly, we show that Prdm1 cKOK14 mice develop SLE-associated symptoms, including ANAs, hypergammaglobulinemia, and kidney immune complex deposition, suggestive of glomerulonephritis, and previous studies reported the dermatitis using the K14-Cre and K5-Cre mouse models." (PMID 28701508, 2017). "In contrast, premature expression of Blimp-1 (PRDM1) during early B cell development promotes the differentiation of autoreactive plasmablasts, ultimately triggering autoantibody production and glomerulonephritis in mouse models." (PMID 40861439, 2025).
Hepatitis (2 papers, 2022 to 2024). Inflammation of the liver. "CNVs on IL1RN and deletions on PRDM1 were significantly linked to IRAE, whereas duplications on CD274 and CNVs on SLCO1B1 were significantly linked to hepatitis." (PMID 35053465, 2022).
Listeria infection (2 papers, 2017 to 2023). "In adoptively transferred Ahr-deficient CD8+ T cells, Prdm1 (encoding Blimp1) mRNA is significantly reduced in TRM cells following Listeria infection." (PMID 37056785, 2023).
lupus-like syndrome (2 papers, 2018 to 2022). "DC-specific deletion of Prdm1, the gene encoding Blimp-1, results in a lupus-like syndrome in female mice that is characterized by elevated serum autoantibodies, enhanced germinal center formation, and increased follicular T helper cells." (PMID 30131810, 2018). "In previous studies, we showed that mice with a conditional deletion of Prdm1 in DCs (Prdm1 CKO) develop a lupus-like syndrome with an increased number of Tfh cells and an increased number of GC B cells." (PMID 35674135, 2022).
metastatic melanoma (2 papers, 2021). A melanoma that has spread from its primary site to another anatomic site. "PRDM1 (PR domain zinc finger protein 1), also known as BLIMP-1, is a tumor-suppressor gene that is an important regulator of neural crest cell (NCC) development and is frequently lost in metastatic melanoma." (PMID 33746966, 2021).
NK/T cell lymphoma (2 papers, 2014 to 2015). "6q21 genetic deletion has been frequently detected in extranodal NK/T cell lymphoma, nasal type (EN-NK/T-NT), and PRDM1 is considered as candidate gene." (PMID 26221594, 2015). "The deletion of 6q21 has been identified as the common genetic aberration in NK/T cell lymphoma (20–43%), and the genes located in the region of 6q21, including POPDC3, PREP, PRDM1, ATG5, AIM1, HACE1, and FOXO3, were reasonably considered the affected candidates." (PMID 26221594, 2015).
osteoarthritis (2 papers, 2018 to 2022). A noninflammatory degenerative joint disease occurring chiefly in older persons, characterized by degeneration of the articular cartilage, hypertrophy of bone at the margins and changes in the synovial membrane. "Three out of the 166 enriched RBPs (PRDM1, RUNX3 and PPARG) were also DE in our dataset and have been extensively linked to osteoarthritis." (PMID 35088088, 2022).
periodontitis (2 papers, 2020 to 2024). An acute or chronic inflammatory process that affects the tissues that surround and support the teeth. "Single-cell sequencing of gingival tissues from periodontitis patients revealed three types of macrophages, including PRDM1 + Macro, NLRP3 + Macro, and C1QA + Macro." (PMID 38689292, 2024).
preeclampsia (2 papers, 2017 to 2024). Preeclampsia is a hypertensive disorder of pregnancy that is characterized by new-onset hypertension with proteinuria presenting after 20 weeks of gestation, and depending on mild or severe forms may initially present with severe headache, visual disturbances, and hyperreflexia. "We found that for stromal cells, the predicted dS2 and dS3 specific regulon targets were enriched with preeclampsia downregulated genes, particularly regulon targets predicted for PRDM1 (LOP down p = 1.75 × 10–18, 21-fold) and for FOXP1 (LOP down, p = 3.8 × 10–14, 9.1-fold)." (PMID 39090334, 2024). "Specifically, predicted stromal cell dS2-specific PRDM1 and FOXP1 targets were enriched in preeclampsia downregulated stromal genes." (PMID 39090334, 2024).
prostate tumor (2 papers, 2022 to 2024). "For example, 13 novel interactors of MPeM-associated genes were associated with prostatic neoplasms (MPeM genes are shown in bold): MET-SLC26A4, DPYD-SULT2A1, CTNNB1-LAMB2, IRS2-MPO, HRAS-ZFP36L2, VEGFB-UCP3, PRDM1-HPGD, NSD1-NPR3, KEAP1-SLC5A5, MET-FOXA3, RHEB-NOS3, HRAS-HBG1 and JAK1-CBR1." (PMID 39516360, 2024).
sarcoma (2 papers, 2021). A usually aggressive malignant neoplasm of the soft tissue or bone. "The transcription factor PRDI-BF1/Blimp1, encoded by the PRDM1 gene, was first described in human sarcoma cell lines as a repressor of the IFN-β gene." (PMID 35154079, 2021).
acute kidney injury (1 paper, 2025). Sudden and sustained deterioration of the kidney function characterized by decreased glomerular filtration rate, increased serum creatinine or oliguria. "Further significantly upregulated transcripts related to inflammatory processes included ADAM19, PD-L1 (CD274), non-canonical NF-kB genes NFKB2 and RELB, furthermore IFITM1, JAML -linked with acute kidney injury - IRX3-linked with metabolic inflammation - and PRDM1-observed in gouty arthritis." (PMID 40281125, 2025).
adenoma (1 paper, 2021). A neoplasm arising from the epithelium. "In the experimental intestinal tumor model of APCMin/+ mice, expression of Sox-9 and PRDM1 were significantly elevated in murine adenoma by gastrointestinal ribosomal dysfunction." (PMID 33972671, 2021). "Stress-driven ribosomal dysfunction elevated intestinal PRDM1 which was notably elevated in the progenitor-rich crypt parts of the gut and adenomas." (PMID 33972671, 2021). "Of note, ribosomal dysfunction significantly increased PRDM1 expression in intestinal epithelia and adenomas, leading to particularly high levels in the crypt parts." (PMID 33972671, 2021).
adult T cell leukemia (1 paper, 2025). "To identify regulators of IL-2 signaling, we performed genome-wide CRISPR-knockout screening in IL-2–dependent cells derived from a patient with adult T cell leukemia (ATL) and found enrichment of single guide RNAs targeting PRDM1, which encodes B lymphocyte–induced maturation protein 1 (BLIMP1)." (PMID 40680114, 2025).
amyloid (1 paper, 2025). "This makes PRDM1 an interesting therapeutic candidate to drive the DAM state in mature microglia, which is hypothesized to be beneficial for amyloid clearance in the context of Alzheimer’s disease." (PMID 41278975, 2025).
B cell lymphopenia (1 paper, 2023). "Despite B cell lymphopenia, the patient BM contained a higher proportion of CD38high PC and expressed elevated levels of transcripts for PRDM1 (encoding BLIMP1) and SDC1 (encoding CD138) compared to two HCs." (PMID 37475856, 2023).
Cervical lymphadenopathy (1 paper, 2017). Enlarged lymph nodes in the neck. "Interestingly, in contrast with WT or heterozygous littermates, ∼80% of Prdm1 cKOK14 mice stochastically developed mandibular and accessory mandibular cervical lymphadenopathy as they aged (≥2 mo)." (PMID 28701508, 2017).